TRUB1 (TruB pseudouridine synthase family member 1)
Description:
Pseudouridine synthase that catalyzes pseudouridylation of mRNAs and tRNAs. Mediates pseudouridylation of mRNAs with the consensus sequence 5'-GUUCNANNC-3', harboring a stem-loop structure. Constitutes the major pseudouridine synthase acting on mRNAs. Also catalyzes pseudouridylation of some tRNAs, including synthesis of pseudouridine(55) from uracil-55, in the psi GC loop of a subset of tRNAs. Promotes the processing of pri-let-7 microRNAs (pri-miRNAs) independently of its RNA pseudouridylate synthase activity. Acts by binding to the stem-loop structure on pri-let-7, preventing LIN28-binding (LIN28A and/or LIN28B), thereby enhancing the interaction between pri-let-7 and the microprocessor DGCR8, which mediates miRNA maturation.
Synonyms: PUS4
Tractability: PROTAC: ubiquitination databases record sites on it; its protein half-life has been measured.
Gene: Protein-coding gene on chromosome 10 (114,938,195 to 114,977,676, forward strand). Ensembl gene ENSG00000165832.
Subcellular location: Nucleus; Cytoplasm, cytosol
Subcellular location (Human Protein Atlas): Vesicles
Gene Ontology:
Molecular function: pre-miRNA binding; protein binding; pseudouridine synthase activity; tRNA pseudouridine synthase activity; tRNA pseudouridine(55) synthase activity; RNA binding
Biological process: mRNA pseudouridine synthesis; positive regulation of pre-miRNA processing; tRNA modification; tRNA pseudouridine synthesis; pseudouridine synthesis; RNA modification; RNA processing
Cellular component: cytosol; mitochondrion; nucleus
Genetic constraint (gnomAD): Loss-of-function variants: 12 observed, 19.23 expected, observed/expected ratio (o/e) 0.62, 90% interval 0.4 to 1.01. The upper end of that interval is the gene's LOEUF score, 1.01, which puts it in group 4 of 6, group 1 being the genes least tolerant of losing a copy. Missense variants: 280 observed, 301.2 expected, observed/expected ratio (o/e) 0.93, 90% interval 0.84 to 1.03. Synonymous variants: 126 observed, 127.17 expected, observed/expected ratio (o/e) 0.99, 90% interval 0.86 to 1.15.
Homologues: Orthologues: chimpanzee TRUB1 (99% identical), macaque TRUB1 (98% identical), dog TRUB1 (93% identical), pig TRUB1 (88% identical), rabbit TRUB1 (83% identical), rat Trub1 (81% identical), mouse Trub1 (80% identical), guinea pig Trub1 (59% identical), tropical clawed frog trub1 (53% identical), zebrafish trub1 (51% identical).
Diseases named in the same sentence as TRUB1 in open-access papers:
TRUB1 is named in the same sentence as 15 diseases in open-access papers, as found by Europe PMC text mining. Sharing a sentence is not in itself a finding about the gene and the disease. The quoted sentences say what the papers report.
glioma (2 papers, 2021 to 2024). A benign or malignant brain and spinal cord tumor that arises from glial cells (astrocytes, oligodendrocytes, ependymal cells). "Six Ψ synthase genes were associated with the prognosis, of which the expression of PUS1, PUS7, RPUSD1 and RPUSD3 was positively associated with the malignancy of glioma (HR > 1), and TRUB1 was negatively associated with the malignant grade (HR < 1)." (PMID 35118063, 2021). "In contrast to other PUSs, TRUB1 seems to maintain a role in the prognoses of gliomas." (PMID 39162904, 2024).
colorectal adenocarcinoma (1 paper, 2025). The most common type of colorectal carcinoma. "The results demonstrated a significant upregulation of TRUB1 in primary colorectal adenocarcinoma (COAD) tissues compared with normal tissues." (PMID 40260225, 2025).
COVID-19 (1 paper, 2024). A disease caused by infection with severe acute respiratory syndrome coronavirus 2. "Overall, this study highlights the significant roles of TRUB1, PLEKHA7, and FABP6 in the development of depression associated with COVID-19." (PMID 39588145, 2024). "In summary, this research highlights the roles of TRUB1, PLEKHA7, and FABP6 as hub genes, the underlying pathways and TF–miRNA networks, and the potential impact of these genes on immune cell activity in the development of depression and COVID-19." (PMID 39588145, 2024). "In this study, the genes TRUB1, PLEKHA7, and FABP6 emerged as central hubs potentially contributing to the pathogenesis of both depression and COVID-19." (PMID 39588145, 2024). "Our findings revealed that TRUB1 and PLEKHA7 expression was decreased, whereas FABP6 expression was increased in both the depression group and the COVID-19 patient group compared with the control group." (PMID 39588145, 2024).
lung carcinoma (1 paper, 2024). "In lung cancer (LUAD, LUSC), DKC1, PUS1, PUS3, PUS7, TRUB1, and TRUB2 expression was mostly negatively correlated with immune cell infiltration." (PMID 39162904, 2024).
multiple sclerosis (1 paper, 2025). A progressive autoimmune disorder affecting the central nervous system resulting in demyelination. "Additionally, a lower level of PROT‐a‐2454 (TRUB1) protein was associated with the occurrence of multiple sclerosis (IVW: OR = 0.8639, 95% CI 0.7520–0.9923, p = 0.0386)." (PMID 39831399, 2025).
Sepsis (1 paper, 2023). Sepsis is defined as life-threatening organ dysfunction caused by a dysregulated host response to infection. "For instance, genes mediating RNA Ψ modification (TRUB1, TRUB2, PUS1, RPUSD3, RPUSD4, PUS7, RPUSD2) were mainly suppressed in sepsis." (PMID 37701433, 2023).
tumor (5 papers, 2021 to 2025). "Further TIMER analysis indicated that the immune system had a good effect on tumor microenvironment, and that the mutations of DARS / GDI2/P4HA2/TRUB1 had important application value in tumor immunology." (PMID 35111402, 2022). "ROC curve analysis yielded AUC values of >0.650 for TRUB1 as a tumor marker and CRC patients with high TRUB1 expression exhibited poorer OS, RFS, and PPS." (PMID 40260225, 2025). "The results showed that TRUB1 expression remained significantly higher in tumor tissues compared with normal tissues in the paired data, further confirming the specific overexpression of TRUB1 in CRC tissues." (PMID 40260225, 2025). "Tumor volume and images demonstrated that the downregulation of TRUB1 significantly reduced tumor growth in the TRUB1-knock-down group." (PMID 40260225, 2025). "We also validated these findings by using GEO datasets (GSE37182 and GSE103512), in which the expression of TRUB1 was consistently higher in COAD tumor tissues than in normal tissues." (PMID 40260225, 2025). "The impact of TRUB1 on tumor proliferation and Ψ modification was examined in TRUB1-knock-down HCT116 cell lines." (PMID 40260225, 2025). "The authors proposed that TRUB1 acts as a suppressor of cell proliferation, and therefore as a tumor suppressor, which is mediated in part by let-7." (PMID 34439361, 2021). "Tumor weights were also markedly lower in the TRUB1-knock-down mice." (PMID 40260225, 2025). "TRUB1 was significantly upregulated in CRC tumor tissues and cell lines." (PMID 40260225, 2025). "In the GSE59612 dataset, the expression of PUS1, PUS7, RPUSD1 and DKC1 were significantly increased in the tumor core tissues relative to tumor marginal tissues and paracancerous tissues; and the expression of TRUB1 was decreased from paracancerous tissue to tumor core tissue." (PMID 35118063, 2021). "In TRUB1-knock-down HCT116 cells, apoptosis increased and tumor growth slowed in nude mice, with a corresponding increase in apoptosis-related proteins and decreased Ψ modification." (PMID 40260225, 2025). "Our findings that TRUB1 knock-down inhibits BIRC3 expression, along with the suppression of TNFα signaling via NFκB, underscore the role of BIRC3 in CRC tumor progression and suggest that TRUB1 may regulate CRC growth through BIRC3-dependent mechanisms." (PMID 40260225, 2025). "In contrast, CNV deletions in the genes TRUB1 and RPUSD4 were maintained in most tumor types." (PMID 39162904, 2024).
cancer (4 papers, 2022 to 2026). A tumor composed of atypical neoplastic, often pleomorphic cells that invade other tissues. "The most notable aberrantly expressed genes were DKC1 and TRUB1, whose expression differed in 29 of the 31 cancer types." (PMID 39162904, 2024). "Our results reveal a transcript stabilization role of Ψ sites installed by TRUB1 in human cancer cells." (PMID 36302989, 2023). "TRUB1 mRNA is widely expressed in various human tissues (especially heart, skeletal muscle and liver), but there are few studies on its relationship with cancer." (PMID 35111402, 2022). "DNA_REPAIR in the P4HA2 gene set and ANGIOGENESIS in the TRUB1 gene set are also two important mechanisms of cancer development." (PMID 35111402, 2022). "Finally, GSVA analysis found that DARS/GDI2/P4HA2/TRUB1 gene sets are closely related to the occurrence of cancer." (PMID 35111402, 2022). "Finally, we conducted a comprehensive evaluation of gene sets using GSVA and we found that the DARS/GDI2/P4HA2/TRUB1 gene sets are closely related to the occurrence of cancer." (PMID 35111402, 2022). "RPUSD1 exhibited markedly elevated expression across pan‐cancer tissues, followed by TRUB2, TRUB1, and PUS3." (PMID 41496500, 2026).
TRUB1 also shares sentences with these, for which no sentence is quoted: breast carcinoma (1 paper); colorectal cancer (1); depression (1); glioblastoma multiforme (1); ovarian carcinoma (1); pancreatic cancer (1); prostate adenocarcinoma (1).